PSMD14 (proteasome 26S subunit, non-ATPase 14)
Diseases named in the same sentence as PSMD14 in open-access papers (continued):
Sharing a sentence is not in itself a finding about the gene and the disease.
cancer (continued). "PSMD14, a proteasome regulatory subunit and deubiquitinase, is a key oncogenic factor in cancer that regulates various physiological processes and malignant tumor behaviors." (PMID 39857292, 2025). "PSMD14 demonstrates elevated mRNA expression across multiple cancer types compared to normal tissues." (PMID 41488674, 2025). "In the present investigation, we leveraged a publicly accessible database to analyze the mRNA expression levels and prognostic relevance of PSMD14 in various cancer types." (PMID 40475775, 2025). "Numerous studies have revealed the role of PSMD14 in inhibiting protein degradation through ubiquitination in cancer." (PMID 40066751, 2025). "The CCK8 assay revealed that overexpression of PSMD14 promoted cancer cell proliferation in MCF-7 cells." (PMID 38017133, 2024). "The CCK8 assay revealed that PSMD14 depletion inhibited cancer cell proliferation in MCF-7, T47D and MDA-MB-175 cells." (PMID 38017133, 2024). "As one oncogene, PSMD14 was shown to deubiquinating several substrates to promote cancer progression." (PMID 38017133, 2024). "Numerous studies have consistently suggested PSMD14 as a promising target for anti-proteasome therapy in diverse cancer types." (PMID 38494478, 2024). "The expression of PSMD14 was significantly higher in patients with larger tumor diameters (85.14% vs 70.09%, P = 0.019) and patients with a family history of cancer (92.16% vs 70.00%, P = 0.002)." (PMID 36632137, 2023). "Since expression of PSMD14 is associated with tumor promotion through interaction with the transcription factor E2F1, our results further support that PSMD14 plays a role in cancer progression of HNSCC." (PMID 35750900, 2023). "Previous research demonstrated that deubiquitination enzyme genes play a role in developing drug resistance in malignant tumors and that interference with PSMD14 or PSMD14 inhibitors can reverse drug resistance in malignant tumors." (PMID 38053170, 2023). "PSMD14 participates in the regulation of cancer occurrence and progression through a variety of molecular mechanisms." (PMID 37350936, 2023). "Consistent with findings in malignant tumors, PCR and western blot analysis revealed that PSMD14 expression was elevated in tumor tissue relative to normal tissue surrounding the tumor in this investigation." (PMID 38053170, 2023). "In both paired and unpaired samples of HCC patients, EZH2, G6PD, LGALS3 and PSMD14 were highly expressed in the cancer and lowly expressed in the paracancer, with statistically significant differences." (PMID 37853322, 2023). "Lastly, PSMD14 is a deubiquitinating enzyme and is overexpressed in several human cancers and predicts poor prognosis." (PMID 35565454, 2022). "Collectively, these results indicate that targeting of PSMD14 triggers paraptosis in MDA-MB 435S cancer cells." (PMID 35269789, 2022). "Many studies have revealed that PSMD14 is an antiproteasome target for tumor therapies of different cancer types." (PMID 33687056, 2021). "Collectively, PSMD14 induces nuclear translocation of PKM2, promoting the expression of downstream genes associated with tumorigenesis and cancer progression." (PMID 34382324, 2021). "In view of the pivotal role of PSMD14 in malignant tumors, THL is potentially interesting as an anti-tumor drug." (PMID 33897885, 2021). "Identification of PSMD14 inhibitor seems to be an alternative way to develop proteasome inhibition to treat cancer." (PMID 33897885, 2021). "As a candidate, PSMD14 is highly expressed in various cancers and performs as an oncogene to promote tumor development and progression 12-14." (PMID 33897885, 2021). "Then, RT-PCR and western blot analysis were used to investigate the expression of PSMD14 in 11 paired tumor and adjacent non-cancer control tissues from LUAD patients." (PMID 32226511, 2020). "Previous studies showed that PSMD14 promoted the progression of several cancers." (PMID 40066751, 2025).
cancer (continued). "Furthermore, mechanistic studies suggested that PSMD14 played a role in promoting cancer development by activating with transcription factors." (PMID 40066751, 2025). "Proteasome 26S subunit non‐ATPase 14 (PSMD14) plays a pro‐carcinogenic role in various cancers." (PMID 40066751, 2025). "Thus, PSMD14 considered a drug target for cancer treatment, especially in the context of inhibiting cancer progression." (PMID 38482057, 2024). "PSMD14 plays an important role in several cancer types as a deubiquitinating enzyme." (PMID 38643468, 2024). "Similarly, our study showed that patients with a family history of cancer were more likely to have high PSMD14 expression." (PMID 36632137, 2023). "Altogether, these results indicate that PSMD14 plays a role in advanced cancers." (PMID 35750900, 2023). "PSMD14 could enhance cancer cells malignancy through the LRPPRC/Beclin1-Bcl-2/SQSTM1 signaling pathway inducing autophagy." (PMID 36632137, 2023). "Furthermore, the high expression of PSMD14 in several cancers has been validated and reported to act as an oncogene in several human cancers." (PMID 36959615, 2023). "Furthermore, inhibition of PSMD14 with o-phenanthroline, thiolutin and capzimin showed anticancer effects in other cancer types." (PMID 35750900, 2023). "Although expression is associated with prognosis and occasionally with advanced cancer features in these studies, correction of the prognostic relevance of PSMD14 for potential confounders was not described." (PMID 35750900, 2023). "We found that PSMD14 expression was an independent predictor of worse DFS, and tumors with high expression of PSMD14 were associated with a 2.89-fold increase in the risk of cancer recurrence or metastasis (HR = 2.89, 95% CI [1.247–6.711], P = 0.013)." (PMID 36632137, 2023). "Importantly, PSMD14 is also involved in several types of tumors and is considered a potential therapeutic target for cancer." (PMID 36632137, 2023). "Collectively, induction of paraptosis by targeting PSMD14 may offer a novel therapeutic strategy against cancers that have acquired resistance to PIs or pro-apoptotic drugs." (PMID 35269789, 2022). "Induction of paraptosis by targeting PSMD14 may provide an attractive therapeutic strategy against cancer cells resistant to proteasome inhibitors or pro-apoptotic drugs." (PMID 35269789, 2022). "PSMD14, a subunit of the 19S regulatory particles of the 26S proteasome, was recently identified as a potential prognostic marker and therapeutic target in diverse human cancers." (PMID 35269789, 2022). "In the present study, we show that targeting PSMD14 may evade the mechanisms through which cancer cells acquire resistance to Bz, a PI targeting 20S proteasome CP, such as the aggresome formation and Nrf1 activation." (PMID 35269789, 2022). "This study shows that Nrf1 activation and aggresome formation, which underlie the PI resistance mechanisms of cancer cells, are not induced by PSMD14 inhibition." (PMID 35269789, 2022). "The PSMD14 inhibitor, capzimin (CZM), inhibits proteasome activity but differs from the 20S proteasome subunit-inhibiting bortezomib (Bz) in that it does not induce aggresome formation or Nrf1 upregulation, which underlie Bz resistance in cancer cells." (PMID 35269789, 2022). "Therefore, PSMD14 acts as an oncogene in several cancers by deubiquitinating diverse protein substrates." (PMID 34382324, 2021). "DUB PSMD14 is reported to be a promising therapeutic target in various cancers." (PMID 33897885, 2021). "PSMD14, a key functional part of the 26S proteasome, is overexpressed in most cancers." (PMID 34234864, 2021). "It will be therefore of interest to evaluate whether the possible contribution of PSMD14 to human cancer occurs through proteosomal-dependent or –independent functions." (PMID 21283576, 2011).
cancer (continued). "Therefore, all of these studies confirmed that PSMD14 acted as an oncogene in cancer." (PMID 36632137, 2023). "The oncogene PSMD14, also known as POH1 or Rpn11 (proteasome 26 S subunit, non-ATPase regulatory 14), has been shown to encode active deubiquitination enzymes in the ubiquitin/proteasome pathway in several cancers." (PMID 38053170, 2023). "Recent research demonstrates that PSMD14 can operate as oncogenes or suppressor genes to influence the formation and progression of cancers by altering the activities of critical proteins, and that PSMD14 may serve as both a prognostic indicator and a possible therapeutic target." (PMID 38053170, 2023). "Therefore, our present results lead us to propose that inducing paraptosis by targeting PSMD14 may provide an attractive therapeutic strategy against cancer cells that exhibit resistance to the PIs and pro-apoptotic drugs." (PMID 35269789, 2022). "Besides, bioinformatics analysis showed that PSMD14 was dramatically elevated in many other cancers, suggesting that PSMD14 may be involved in the malignant progression of multiple cancers including HNSCC." (PMID 33456565, 2021). "Therefore, PSMD14 plays complex functions in various cancers." (PMID 34382324, 2021). "Therefore, PSMD14 is considered to become a promising target for cancer therapy." (PMID 33897885, 2021). "Future investigations should emphasize elucidating the role of PSMD14 within various tumor microenvironments and its potential roles in alternative signaling pathways, particularly within the immune microenvironment, as this could reveal new avenues for cancer immunotherapy." (PMID 40475775, 2025). "Consequently, PSMD14 could promote cancer development through multiple pathways." (PMID 40066751, 2025). "Most of these genes were cell cycle-related genes, including CHEK1, CDK1, RUVBL2, PSMD14, SUPT5H, RBX1, and AURKA, across 28 cancer types." (PMID 38972884, 2024). "In contrast, accumulating evidence reveal that PSMD14 also suppress the ubiquitination and degradation of specific proteins, such as SNAIL 37, GRB2 38 and ALK2 receptor 39, to promote cancer progression." (PMID 33456565, 2021). "The in vitro and in vivo assays suggested that PSMD14 depletion significantly impaired tumor growth, chemoresistance in HNSCC by antagonizing E2F1/Akt/SOX2 axis-mediated cancer cell stemness." (PMID 33456565, 2021). "Using melanoma data sets from Cancer Cell Line Encyclopedia15, the gene set related to TGF-β signaling was significantly enriched among the top 1% genes negatively correlated with PSMD14 expression." (PMID 33154524, 2020). "In contrast to earlier investigations concerning PSMD14 in LUAD, our study offers a comprehensive examination of PSMD14 utilizing pan-cancer analysis, functional enrichment assessment, immune infiltration evaluation, JAMM family correlation assessment, and prognostic analysis." (PMID 40475775, 2025). "Furthermore, the results of cellular function assay are consistent with recent studies, suggesting that the oncogenic role of PSMD14 and SORT1 in various cancer." (PMID 36959615, 2023). "Patients with a family history of cancer were more likely to have high PSMD14 expression (yes vs no; 92.16% vs 70.00%, P = 0.002)." (PMID 36632137, 2023). "Recently, the PSMD14 inhibitor capzimin (CZM), a derivative of quinoline-8-thiol, stabilized a subset of proteasome substrates in treated cells and inhibited the proliferation of cancer cells." (PMID 35269789, 2022). "26S proteasome non-ATPase regulatory subunit 14 (PSMD14) is a 310-residue DUB enzyme important for Ub recycling from the proteasome substrate proteins, and its upregulation has been reported in cancer, where it promotes proliferation and migration of cancer cells." (PMID 32455657, 2020).
cancer (continued). "DUBs are critical key players in diverse processes such as (i) spermatogenesis (e.g. USP2, USP8, USP9y, USP14, USP26, Uchl-1, Uchl-3 and CYLD), (ii) cancer biology (e.g. USP7, USP10 and USP11), and (iii) stemness and differentiation (e.g. USP7, USP9x, USP22, USP44 and Psmd14)." (PMID 28659380, 2017). "Although the deubiquitinating enzyme 26S proteasome non-ATPase regulatory subunit 14 (PSMD14) is known to exert oncogenic functions in various cancers, its potential role in regulating tumor immune evasion remains unclear." (PMID 41981629, 2026). "In our investigation of LUAD, our findings demonstrated significantly increased expression levels of PSMD14, TTF1, KI67, CK7, and NapsinA in tumor tissues when compared to adjacent non-cancerous tissues, further supporting the role of PSMD14 across various cancer types." (PMID 40475775, 2025). "Besides, PSMD14 could also stabilize E2F1, which enhanced E2F1 target gene expression and cancer progression in head and neck squamous carcinoma." (PMID 38017133, 2024). "PSMD14 plays an oncogenic role by stabilizing proteins, such as transcription factor AP-1, E2F1, SMAD3, EMT crucial transcription factor SNAIL,SLUG, translational regulator GRB2, BMP type 1 receptor ALK2, aerobic glycolysis enzyme PKM2, promoting cancer proliferation, metastasis and chemoresistance." (PMID 38327651, 2023). "Moreover, contactin-5 (CNTN5), 26S proteasome non-ATPase regulatory subunit 14 (PSMD14), hepatic and glial cell adhesion molecule (HEPACAM) and hepatocellular Carcinoma, Down-Regulated 1 (HEPN1) are four genes associated with suicidality." (PMID 36979315, 2023). "Recently, PSMD14 inhibitors, such as o-phenanthroline (OPA) and CZM, were reported to reduce the viability of MM cells by inducing an unfolded protein response (UPR) and stabilizing proteasome substrates, thereby exerting cytotoxicity against even Bz-resistant cancer cells." (PMID 35269789, 2022).
tumor (55 papers, 2015 to 2026). "Our results reveal that increased expression of PSMD14 is associated with poorer clinical outcomes, indicating its potential role in tumor progression and mechanisms of immune evasion." (PMID 40475775, 2025). "Collectively, these findings indicate that elevated PSMD14 expression is associated with an immunosuppressive and inflammatory tumor microenvironment (TME) in LUAD." (PMID 41488674, 2025). "PSMD14 is also known as POH1/Rpn11, and its high expression is associated with tumor progression, high tumor grade, reduced susceptibility to cytotoxic drugs, and poor prognosis." (PMID 38482057, 2024). "Then, we calculated the scores of tumor samples using IHC and evaluated the association between the expression of PSMD14 and patient characteristics to determine if PSMD14 is a survival-predictive biomarker." (PMID 38053170, 2023). "We further found that higher PSMD14 expression was correlated with higher risk group (younger age group, ≤20.83 years of age), metastasis within 5 years and higher grade of tumor." (PMID 34383385, 2022). "Upregulation of PSMD14, in hepatocellular carcinoma, has been associated with tumor promotion through E2F transcription factor 1 (E2F1) stabilization and its target genes." (PMID 33805973, 2021). "Loss-of-function assays showed that PSMD14 depletion undermined tumor initiation, growth and chemoresistance of HNSCC cells." (PMID 33456565, 2021). "The PSMD14 level was associated with tumor size, lymph node invasion, and TNM stage in LUAD patients." (PMID 32226511, 2020). "PSMD14 expression was significantly associated with tumor size, lymph node invasion, and TNM stage in LUAD patients." (PMID 32226511, 2020). "Collectively, these results imply that PSMD14 may play a critical role within the tumor microenvironment and could be implicated in the initiation and progression of tumors." (PMID 40475775, 2025). "Another protein that has been linked to slow tumor progression and an advanced stage is PSMD14." (PMID 39199313, 2024). "Silencing of PSMD14 suppressed tumor cell growth, and was associated with down-regulation of GPX4." (PMID 36632137, 2023). "Moreover, PSMD14 was upregulated in breast cancer tissues and found to be associated with clinical tumor stage and poorer overall survival." (PMID 35884607, 2022). "Through regulating protein deubiquitination and stabilization, PSMD14 is implicated in various biological processes, including differentiation 6, cell viability 7, pluripotency 8, autophagy 9, DNA break responses 10, 11 and tumor progression." (PMID 33897885, 2021). "The Wilcoxon rank-sum test revealed a significant difference in PSMD14 expression between normal and tumor tissues (P < 0.001), indicating a marked expression disparity between the two groups." (PMID 41488674, 2025). "The potent anti-tumor efficacy of Capzimin, demonstrated both in vitro and in vivo, validates the therapeutic value of PSMD14 inhibition." (PMID 41488674, 2025). "It is noteworthy that, within the tumor group, PSMD14 expression was present in DCs, tissue stem cells, endothelial cells, and epithelial cells, whereas, in the control group, its expression was confined to DCs and macrophages." (PMID 40475775, 2025). "Conversely, a significant reduction in PSMD14 expression was noted in the tumor tissues of the kidney chromophobe (KICH)." (PMID 40475775, 2025). "To further investigate the oncogenic role of PSMD14 in vivo, we subcutaneously injected stable PSMD14‐overexpressing and PSMD14‐knockdown PANC‐1 cells into nude mice to establish a xenograft tumor model." (PMID 41051446, 2025). "The exploration of PSMD14’s function in LUAD is motivated by its possible relevance in tumor advancement and immune evasion." (PMID 40475775, 2025). "The PSMD14 inhibitor Capzimin exhibited potent anti-tumor effects in vitro and in vivo, and combination therapy with the TGF-β inhibitor galunisertib demonstrated enhanced efficacy." (PMID 41488674, 2025).